VIM (vimentin)
Diseases named in the same sentence as VIM in open-access papers (continued):
Sharing a sentence is not in itself a finding about the gene and the disease.
tumor (continued). "The IHC staining revealed increased expression of E-cadherin, and decreased expression of Ki-67, Vimentin, snail, phosphorylation of Akt, S6, and 4EBP1 in the high-dose β-lap-treated tumour group compared with the other groups." (PMID 28578385, 2017). "HIF-1α is a crucial transcription factor that contributes to the tumor EMT, which is characterized by the loss of cell adhesion, repression of E-cadherin expression, acquisition of the mesenchymal marker vimentin, and increased cell motility and invasiveness." (PMID 28449718, 2017). "Together, these results indicate that miR-320a downregulates USP14 and vimentin and functions as a tumor suppressor in GC cells." (PMID 27448976, 2017). "Immuno-staining with a human-specific anti-vimentin antibody revealed the presence of infiltrating cells and the formation of several tumor foci in the striatum of the control animals." (PMID 28358371, 2017). "Vimentin and ASMA are applied as markers for mesenchymal or transformed cells, in our case of cancer associated fibroblasts or transformed tumour cells due to epithelial to mesenchymal transition." (PMID 28592821, 2017). "The immunohistochemical staining of xenograft tumor with E-cadherin and vimentin validated in vitro results." (PMID 28406456, 2017). "Instead, pan-CK expression occurs, which is variably co-expressed with vimentin, thus favouring the sarcomatoid nature of the tumour." (PMID 29182526, 2017). "In serial section of tumor samples from ICC patients, the high level of B7-H4 in tumor tissues were positively consistent with loss of E-cadherin and strong staining for Vimentin and Snail." (PMID 29235470, 2017). "Immunocytochemically, the tumour cells showed a strong nuclear expression of brachyury and a cytoplasmatic positivity of vimentin, cytokeratins, and S100-protein." (PMID 28515451, 2017). "We also isolated the total protein of tumor, western blot assay suggested epithelial marker E-cadherin level was significantly increased, mesenchymal marker Vimentin was significantly reduced, confirming PTTG1 regulated EMT and metastasis." (PMID 27893422, 2017). "As seen in WT tumors, in all tumors except 468-shCDH1-B and to some extent 468-shCDH1-D, vimentin-positive cells were observed at the invasion front along the tumor-stroma border and also at the tumor-necrosis border, indicative of EMP." (PMID 28750639, 2017). "Treatment with the autophagy inhibitor 3MA suppressed the induction by tumor-derived myeloid cells of EMT-associated molecules (N-cadherin and vimentin) and invasion-related phenotypes of A549 and patient-derived primary NSCLC tumor cells (PLC-HU1)." (PMID 28686632, 2017). "The expression of EMT-related markers were also changed by combination treatment in mice tumor tissues, as the level of E-cadherin was upregulated while vimentin expression was reduced." (PMID 28915640, 2017). "To evaluate the role of hMSCs in EMT process in vivo, we stained the tumor sections with epithelial marker E-cadherin and mesenchymal marker Vimentin." (PMID 28542126, 2017). "In the in vivo experiment, the data showed that JPJD can upregulate the expression of E-cadherin and downregulate the expression of Vimentin in the orthotopic CRC tumor tissues, which also showed the significance of JPJD on inhibiting EMT in vivo." (PMID 28299321, 2017). "Knocking down IL-6 can increase E-cadherin expression and decrease vimentin expression via Stat3 pathway, which also reduces tumor invasion in vivo." (PMID 28973968, 2017). "Metastasizing tumor cells show increased expression of the IF protein vimentin, which, therefore, has been used to diagnose invasive tumors in the clinic for decades, and is used as a canonical marker of epithelial-to-mesenchymal transition." (PMID 28117759, 2017).
tumor (continued). "GSK-LSD1 inhibited tonsillar SCC patient-derived tumor xenografts and inhibited CCN2/CTGF, MMP13, LOXL4 and vimentin expression whereas the expression of the tumor suppressor E-cadherin increased." (PMID 29088714, 2017). "Studies have suggested that the expression of vimentin positively correlates with tumour metastasis." (PMID 28831201, 2017). "As 4T1 cells have been previously demonstrated to express modest amounts of vimentin and robust levels of E-cadherin in vitro, expression of both proteins in vivo was perhaps unsurprising, given the aggressive phenotype of the tumours." (PMID 27711075, 2016). "Immunohistochemical experiments demonstrated that most tumor cells were positive for vimentin, CK, and EMA." (PMID 27784295, 2016). "The tumor was positive for vimentin, CD10, α1-antichymotrypsin, α1-antitrypsin, β-catenin, neuron-specific enolase, synaptophysin, and progesterone receptor." (PMID 30631811, 2016). "In our study, we also observed an overexpression of vimentin in the tumor samples in comparison with the control bronchiolar epithelial tissue." (PMID 26993609, 2016). "HCC patients with high OPN and high vimentin had the poorest prognosis with the lowest OS and highest probability of tumor recurrence." (PMID 26824421, 2016). "The tumours resulting from implantation of the 4T1 cells were morphologically heterogeneous, with abundant expression of vimentin." (PMID 27711075, 2016). "Immunohistochemically, the tumor cells were positive for vimentin, cell adhesion molecule 5.2 (CAM5.2), epithelial membrane antigen (EMA), and E26-related gene (ERG); they were negative for AE1/AE3, CD34, S100, smooth muscle actin, and CD31." (PMID 27776545, 2016). "For evaluation of anti-tumor therapeutic efficacy, various formations composed of DOX and/or vimentin siRNA were further analyzed in xenograft Huh7 tumor mouse model." (PMID 28335269, 2016). "In vivo, xenografted DDA1-overexpressing tumor cells had lower E-cadherin levels, but higher expression of nuclear β-catenin, N-cadherin, vimentin, and Snail than controls." (PMID 26942699, 2016). "To identify the potential underlying mechanisms for this effect, we subjected xenograft tumor tissues to Western blot analyses against p-AMPK, p-mTOR and mesenchymal phenotype-associated proteins (i.e., slug, vimentin, N-cadherin, and ZEB1)." (PMID 27223262, 2016). "Expression of proteins characteristic of mesenchymal cells (N-Cadherin, Vimentin, SNAIL, SLUG) and loss of epithelial markers (E-Cadherin) correlates with tumor progression and poor prognosis." (PMID 27658496, 2016). "Tumor cells during migration reduce or even abolish cytokeratin filaments and increase/or de novo express α-actin and vimentin; this is commonly seen in pleomorphic carcinomas, carcinosarcomas, high-grade squamous cell and adenocarcinomas, and SCLC." (PMID 27018053, 2016). "Vimentin expression in tumour cells is a sign of mesenchymal differentiation and then associated with shorter survival." (PMID 27689078, 2016). "Immunohistochemically, ERMS typically express skeletal muscle markers: Tumor cells usually stain positive for vimentin, desmin, myogenin and myoglobin." (PMID 27357857, 2016). "We assessed the cancer cell and fibroblasts fractions in mouse xenograft tumor by immunofluorescence staining using an antibody specific for human vimentin, which A549 cells fail to express." (PMID 27541266, 2016). "This analysis unveiled that those samples with a tumor diameter larger than 3.7 cm were heterogeneous for Vimentin immunostaining with an accuracy of 72.5 %." (PMID 26951092, 2016). "The results revealed that higher protein levels of vimentin were significantly associated with ALT (P = 0.041) and tumor differentiation (P < 0.001)." (PMID 26824421, 2016). "The protein expression levels of E-cadherin, N-cadherin, claudin-1, and vimentin were significantly higher in CLM than in primary tumor tissues (p < 0.05)." (PMID 27152521, 2016).
tumor (continued). "The impeded cancer progression was due to the inhibitory effect of metformin on STAT3-ERK-vimentin and fibronectin-integrin signaling to decrease tumor cell invasion and de-differentiation." (PMID 27145454, 2016). "Conversely, the more mesenchymal tumors (PtH, PtAM spheres, and PtAB spheres) expressed vimentin in both the epithelial cancer cells as well as the stromal cells of the tumor, and had very low expression of CD44v8-10." (PMID 27253518, 2016). "Pre-treatment circulating methylated vimentin correlated with both tumor bulk and the obtainment of clinical benefit for study treatment." (PMID 27542211, 2016). "In invasive ductal breast cancer, budding cell populations had lower membranous localization of E-cadherin and higher vimentin cytoplasmic levels than center tumor cells." (PMID 27136592, 2016). "The remaining AZD8931-resistant tumour resembled the vehicle-treated tumours, being both E-cadherin and vimentin positive." (PMID 26721874, 2016). "Taken together, these data indicate that 86C binds to vimentin on the GBM tumor cell surface and rapidly internalizes upon interaction with CSV with time-dependent kinetics." (PMID 27713131, 2016). "Co-expression of YAP/TEAD4-FL strongly induced EMT in two primary tumour cell lines as judged by increased levels of N-cadherin and Vimentin; however, the expression of TEAD4-S or RBM4 suppressed the induction of EMT markers." (PMID 27291620, 2016). "The augmented invasiveness was accompanied by attenuated SMAD7 and enhanced Vimentin both at the edge and the interior areas of the tumours, as revealed by immunohistochemistry (IHC) analyses." (PMID 27996004, 2016). "The results of IHC staining analysis showed that vimentin was expressed in the cytoplasm of mangy tumor cells." (PMID 27966589, 2016). "Increasing of vimentin expression in various epithelial cancers has been reported that vimentin in cancer correlates with increased tumor growth, invasion, and poor prognosis." (PMID 28335269, 2016). "But we have chosen for observing the expression of vimentin in the ductal part of the tumor, which is of epithelial origin." (PMID 26906973, 2016). "IHC analysis of tumour sections stained with anti-E-cadherin, anti-vimentin and anti-β-catenin antibodies revealed that ORI inhibited EMT as well as Wnt/β-catenin pathway in vivo." (PMID 27453691, 2016). "Immunohistochemical experiments revealed that most tumor cells were positive for vimentin, CK, and EMA, which confirmed the diagnosis of MA." (PMID 27784295, 2016). "We further observed an overexpression of vimentin in the tumor samples, along with the control bronchiolar epithelium." (PMID 26993609, 2016). "We show that the loss of BRG1 is associated with the loss of E-cadherin and up-regulation of Vimentin in primary tumors, which explains why BRG1 loss is associated with a poor prognosis in multiple tumor types." (PMID 27486753, 2016). "We also observed co-localization of CK19 and S100A4 as well as CK19 and vimentin in early tumor lesions." (PMID 27323406, 2016). "Vimentin and CD34 are associated with tumor growth, invasion and metastasis, and Ki-67 is a marker of tumor cell proliferation." (PMID 26871290, 2016). "Immunohistochemically, the tumor cells were positive for vimentin, cell adhesion molecule 5.2, epithelial membrane antigen, and E26-related gene." (PMID 27776545, 2016). "The second case was diagnosed with the same method as in the specimen; the tumor was negatively stained by keratin, S100, and thyroglobulin, and positively stained by vimentin, desmin, and smooth muscle actin." (PMID 27080750, 2016). "Despite the preclinical data demonstrating clear modulation of vimentin with azacitdine, it is still unclear the impact of azacitidine on actual tumor tissue." (PMID 27542211, 2016). "Vimentin is a filamental protein expressed in mesenchymal cells, often recorded as a marker of tumour cell invasion via its expression during activation of the epithelial-mesenchymal transition (EMT)." (PMID 26923772, 2016).
tumor (continued). "Immunofluorescence analysis of the tumor biopsies from both group indicated mesenchymal markers Vimentin and Snail were higher in FD tumors and very weak E-cadherin signal; stemness marker Oct4 in FD tumor was also higher as compared to the FC counterpart." (PMID 27119349, 2016). "Vimentin expression in the tumour was detected in 29 samples (28.2%) and was correlated to L1CAM expression (Spearman's rho 0.349, P=0.001)." (PMID 27028855, 2016). "We further examined the expression of E-cadherin, N-cadherin, and vimentin in the orthotopic tumor samples." (PMID 26733151, 2016). "Immunohistochemical analysis showed that the majority of tumor cells in Scc25 xenografts exhibited stronger vimentin staining and weaker E-cadherin staining than Scc25-AEG-1-siRNA cells." (PMID 26689985, 2016). "This loss of E-cadherin was accompanied by expression of the mesenchymal marker vimentin in the resistant spindle cell tumours, indicating that these resistant tumours had undergone EMT." (PMID 26721874, 2016). "Surprisingly, we found that the expression of Vimentin was strikingly reduced in five of CRABP2 OE tumor tissues, suggesting that CRABP2 was of great possibility to regulate cell metastasis by inhibiting Vimentin expression in vivo." (PMID 26839961, 2016). "Ki67 and vimentin are well-characterised markers of tumour cell proliferation and the epithelial-mesenchymal transition (EMT), respectively." (PMID 26923772, 2016). "When EGFR is activated or E-cadherin is inactivated, the most obvious changes occur on the tumor cell membrane, while cytoplasmic vimentin is one of the best indicators of EMT in HNSCC." (PMID 27172790, 2016). "Further analysis of the tumours revealed that all vehicle-treated tumours expressed both E-cadherin and vimentin." (PMID 26721874, 2016). "The anti-vimentin antibody showed cross-reactivity with some white blood cells, but the anti-cytokeratin antibodies were more specific for tumor cells with less cross-reactivity with white blood cells." (PMID 27369977, 2016). "Immunohistochemical studies showed positive results for vimentin, actin, and desmin in tumor tissue, whereas other markers including pan-cytokeratin, thyroglobulin, and TTF-1 were negative." (PMID 27080750, 2016). "In the early tumour cell’s transition to a motile phenotype, the change in expression from e-cadherin to vimentin is well known and described." (PMID 27447934, 2016). "By histochemical analysis, the tumor was shown a part of positive for desmin and myoglobin and a part of positive for synaphtophysin and vimentin." (PMID 27250580, 2016). "Our results corroborate those seen in tumour biopsies, with a diminished OS observed in patients with vimentin-expressing CTCs and those with Ki67-expressing CTCs." (PMID 26923772, 2016). "For instance, several EMT markers, such as vimentin and N-cadherin, are commonly expressed in circulating tumor cells from patients with relapsed metastatic PCa." (PMID 27003818, 2016). "The AZD8931-responsive tumour was also both E-cadherin and vimentin positive, although the number of vimentin-positive tumour cells was much lower than in the vehicle-treated tumours." (PMID 26721874, 2016). "Baseline methylated vimentin correlated with tumor volume (P<0.001) and higher levels of baseline methylation correlated with the obtainment of stable disease (P=0.04)." (PMID 27542211, 2016). "In many cancers, vimentin overexpression correlates well with accelerated tumor growth, invasion, and poor prognosis." (PMID 26910370, 2016). "Especially at the tumor invasion front, the increased expression of vimentin was observed in 55 % (23 out of 42) patients with recurrence, and in 61 % (20 out of 33) patients with poor survival." (PMID 26769084, 2016). "Immunohistochemically, the tumor cells show positive reactivity for S-100 protein (in 85% to 100% of cases), neuron specific enolase, and vimentin." (PMID 27525129, 2016).
tumor (continued). "The expression levels of SNAI2 and VIM varied across the TCGA sample set, with median levels generally lower in tumour samples compared to control." (PMID 27876705, 2016). "Analysis revealed that the tumor cells were immunopositive for vimentin, microphthalmia transcription factor, S100, CD1a, CD10, CD63, and folliculin, but immunonegative for cytokeratin, α-smooth muscle actin, HMB45, Melan-A, and PNL-2." (PMID 27871249, 2016). "As we had shown that CRABP2 regulated cell migration via EMT in vitro, we further examined the expression of Vimentin in CRABP2 OE tumor tissues dissected from the nude mice, in comparison with that in Vector tumor tissues." (PMID 26839961, 2016). "For example, lncRNA-AOC4P has been shown to act as an HCC tumor suppressor by enhancing vimentin degradation and suppressing EMT progress." (PMID 27002617, 2016). "Administration of 5-MTP to a murine xenograft tumor model reduced vimentin protein expression in the tumor tissues compared to vehicle control which was correlated with reduction of metastasis in the 5-MTP treated mice." (PMID 27145282, 2016). "Tumour sections stained with anti-E-cadherin, anti-vimentin and anti-β-catenin antibodies revealed that ORI inhibited EMT, as well as the Wnt/β-catenin pathway in vivo." (PMID 27453691, 2016). "As with the primary resistant tumours, the two spindle cell AZD8931-resistant tumours had lost E-cadherin and were strongly vimentin positive." (PMID 26721874, 2016). "Combined with the observation that vimentin is critical for tumor metastasis, the findings of our current study indicated that resistin induces tumor invasion via ERM-mediated vimentin induction." (PMID 26729407, 2016). "In the first case, we were able to identify the mesenchymal phenotype of circulating tumor cells, consisting in Vimentin expression." (PMID 27502239, 2016). "Here, for the first time, we describe a novel mAb, 86C, which binds CSV on cancer tumor initiating and leads to the internalization of the vimentin and the consequent apoptosis of target cells." (PMID 27713131, 2016). "The tumor cells were diffusely positive for vimentin, focally positive for S-100 and bcl-2, sparsely positive for cytokeratin, and negative for EMA and c-kit." (PMID 27068820, 2016). "Immunohistochemical staining of the tumor reveals high positivity for desmin, vimentin, ER, and PR receptor; however it generally reveals negativity for S-100 protein." (PMID 27274880, 2016). "The mean intensity of fluorescence (Total MMPs/Tumor Size), Vimentin and β-catenin (especially in nuclear) decreased, while E-cadherin increased significantly in the Si-Nestin treated group as compared to the Si-Control group." (PMID 27412382, 2016). "Further, staining of tumours for human specific vimentin revealed that the majority of cells are of human origin while few unstained cells are mouse stroma-derived." (PMID 27853253, 2016). "Administration of TGF-β1 neutralizing antibody blocked the increased levels of Snail and Vimentin as well as the down-regulation of E-cadherin in GFAT1-depleted tumor cells." (PMID 27509259, 2016). "Our findings demonstrate that baseline increased circulating methylated vimentin correlates with greater tumor bulk." (PMID 27542211, 2016). "Previous in vitro experiments have hinted at an active role for Axl–a novel downstream effecter of vimentin in regulating EMT of tumor cells, in tumor biology." (PMID 26824421, 2016). "Lung sections from mice injected with FZD7 knockdown or control MA-2 cells were stained with the anti-phospho-Histone H3 (pHH3) antibody (to label cells at metaphase) and the anti-human vimentin antibody (to label tumor cells)." (PMID 26808375, 2016). "In fact, vimentin expression in tumour cells from resected PDAC patients is an indicator of poor outcome (P < 0.01) and was associated with poorly differentiated tumour phenotype (P < 0.01)." (PMID 27689078, 2016).